NF1 (neurofibromin 1)
Diseases named in the same sentence as NF1 in open-access papers (continued):
Sharing a sentence is not in itself a finding about the gene and the disease.
glioma (continued). "Additionally, the relationship to decreased OS has been demonstrated before between NF1 mutations and both low grade gliomas and glioblastoma." (PMID 41212363, 2025). "Nevertheless, treatment resistance to molecular monotherapy remains a challenge, and mechanisms underlying MEK inhibitor resistance in NF1-mutant glioma are unknown." (PMID 40985888, 2025). "Optic gliomas formed after both types of injury in mice with nf1-deficient preneoplastic inhibitors, suggesting that NF1 may play a protective role in TBI." (PMID 39335533, 2024). "Somatic mutations in NF1 gene were associated with shorter survival in glioma and lung cancers." (PMID 39277826, 2024). "Constitutional mismatch repair (MMR) deficiency (CMMRD) is a tumour predisposition syndrome that shares some clinical features with NF1, and both syndromes are associated with the occurrence of café-au-lait spots, but also high-grade glioma, acute myeloid leukaemia or rhabdomyosarcoma." (PMID 38448973, 2024). "Gliomas associated with the NF1 mutation have a better prognosis for sporadic gliomas." (PMID 37959175, 2023). "NF1-associated gliomas involve the optic nerve, optic chiasm and/or optic radiations." (PMID 37959175, 2023). "To date, limited drug sensitivity studies have been performed on NF1 associated High Grade Gliomas." (PMID 36730269, 2023). "NF1 acts as a tumor suppressor gene is highly mutated in gliomas." (PMID 36352461, 2022). "Interestingly, 11 of the 47 gliomas in our study cohort demonstrated two or more somatic events contributing to inactivation of the remaining wildtype NF1 allele." (PMID 35945463, 2022). "In addition, we revealed that the NF1 and IDH1 mutations were mutually exclusive suggesting NF1 mutation has independent molecular mechanism involved in glioma biology." (PMID 36352461, 2022). "The NF1-associated gliomas epigenetically clustering with either HGAP or IDH-wildtype glioblastoma had worse outcomes compared to the novel NF1-associated pilocytic astrocytoma methylation class, but appeared to have better prognosis than sporadic IDH-wildtype glioblastoma." (PMID 35945463, 2022). "To surmount this barrier, we leveraged human induced pluripotent stem cell (hiPSC) engineering to generate low-grade gliomas (LGGs) harboring the two most common pediatric pilocytic astrocytoma-associated molecular alterations, NF1 loss and KIAA1549:BRAF fusion." (PMID 35986378, 2022). "Whether these NF1-associated gliomas represent distinct biologic entities and follow different clinical courses with unique therapeutic vulnerabilities compared to sporadic gliomas with shared histologic diagnosis is poorly understood." (PMID 35945463, 2022). "Molecularly, these gliomas are driven by inactivation of the NF1 tumor suppressor gene which encodes the neurofibromin protein that functions as a negative regulator of the RAS family of oncoproteins and downstream mitogen-activated protein (MAP) kinase signaling pathway." (PMID 35945463, 2022).
glioma (continued). "In contrast, while 5/6 NF1-associated gliomas epigenetically aligning with IDH-wildtype glioblastoma harbored either CDKN2A homozygous deletion or CDK4 amplification similar to NF1-associated HGAP, only one of these six tumors had ATRX mutation, and none exhibited piloid features." (PMID 35945463, 2022). "Moreover, deficiency of NF-1 in IDH-wt gliomas leads to increased macrophage recruitment and is seen most frequently in the mesenchymal subtype." (PMID 36589241, 2022). "In contrast to the molecular low-grade group that formed a single distinct epigenetic cluster, we found that NF1-associated high-grade gliomas are epigenetically diverse, with most cases aligning with either HGAP or various subclasses of IDH-wildtype glioblastoma." (PMID 35945463, 2022). "NF1 (neurofibromatosis type 1) is a broad predisposition syndrome for various tumors, also for gliomas and most frequent tumor suppressor syndrome, with an incidence of 1/3000 births and a regulator of the RAS signaling pathways, essential for regulating cell differentiation and growth." (PMID 34687436, 2022). "Two distinct molecular groups were identified among the 47 NF1-associated gliomas." (PMID 35945463, 2022). "Gliomas in patients with NF1 loss have a prevalence of ALT ranging between 29% and 69%." (PMID 34069193, 2021). "Frequently, other stigmata of NF1 occur alongside NF1-associated gliomas." (PMID 33779771, 2021). "Previously, a low level of cAMP could evidently exacerbate gliomagenesis in susceptible Nf1 mice; thus, cAMP-based targeted therapy for glioma has been extensively adopted in mice." (PMID 34777696, 2021). "This suggests that ATRX loss in the presence of NF1 mutation may be sufficient to induce ALT in gliomas." (PMID 34069193, 2021). "Although NF1-associated gliomas are usually PA, patients with NF1 may present high-grade gliomas, especially in adulthood, with a poor prognosis." (PMID 32486389, 2020). "We also observed that Im2, which was enriched in NF1 mutation, was characterized by high macrophages, in agreement with the finding that tumors with NF1 mutation had increased macrophage infiltration in glioma." (PMID 32392361, 2020). "These emerging reports suggest that NF1-associated tumors, including gliomas, may be responsive to immunotherapy, which should be explored in clinical trials." (PMID 31906320, 2020). "Nevertheless, the overall survival remains poor in NF1-associated high-grade gliomas, with reports of enhanced toxicity when the standard therapy (gross total resection followed by fractionated radiotherapy, with concurrent and adjuvant temozolomide) is administered." (PMID 31906320, 2020). "Furthermore, we discuss the recent notable advances in the developing therapeutic landscape for NF1-associated gliomas including clinical trials and collaborative efforts." (PMID 31906320, 2020). "Furthermore, “loss of ATRX in NF1 HGGs is unique when considered within the genetic contexts associated with ATRX mutations in sporadic gliomas,” in which they are typically associated with pediatric H3 K27M-mutant DMGs." (PMID 32582540, 2020).
glioma (continued). "TERT = TERT copy number variant gain in NF1-Glioma and TERT promotor expression in LGm6 group." (PMID 31906320, 2020). "We have previously shown that CD44 is the CCL5 receptor on Nf1-deficient high-grade glioma cells." (PMID 32358581, 2020). "We then sought to investigate whether mutations, specifically nonsense or missense mutations, found within the NF1-LRD domain will affect the invasiveness of glioma cells." (PMID 30967630, 2019). "Representative images of telomere lengths in NF1-associated gliomas are illustrated." (PMID 31462295, 2019). "RECQL4 variants were also present in two ALT-positive, ATRX intact NF1-gliomas." (PMID 31462295, 2019). "Some other NF1-associated tumors worth mentioning (e.g. gliomas, GISTs, pheochromocytomas) may have been referred to as malignant in the literature." (PMID 30479396, 2018). "NF1 has been reported to be associated with various types of cancers, especially tumors derived from the embryogenic neural crest, including pheochromocytoma, leukemia, glioma, rhabdomyosarcoma, astrocytoma and neurofibrosarcoma." (PMID 25889501, 2015). "Based on these results, we performed a human genome-wide association study and found that polymorphisms in the adenylate cyclase 8 gene were correlated with glioma risk in NF1 but in a sex-specific fashion, elevating risk in females and suppressing risk in males." (PMID 25985759, 2015). "Thus, in both medulloblastoma and NF1-associated glioma, primary oncogenic events are mechanistically complemented by decreased levels of cAMP." (PMID 26283963, 2015). "Interestingly, polymorphism analysis of gliomas in NF1 patients found correlation between specific polymorphisms in the human adenylate cyclase 8 gene with glioma development in a sex-specific manner." (PMID 26000738, 2015). "Since loss of NF1 is a hallmark of mesenchymal glioma, it is possible that an increased subpopulation of Olig2+ cells may be a driver of oncogenesis in that tumor subtype." (PMID 23451236, 2013). "Moreover, recent studies demonstrate that in the Nf1-loss model of glioma in mice, mTORC2 activity promotes neural stem cell proliferation and expansion in a manner dependent on Rictor expression." (PMID 23077666, 2012). "Additionally, excess Alk expression or activation has been reported in astrocytomas, gliomas, neuroblastomas and pheochromocytomas, in which loss of NF1 expression has also been found." (PMID 21949657, 2011).
glioma (continued). "In the case of gliomas induced by NF1 loss, the most likely cell of origin is determined by whether the initiating oncogenic events generate an appreciable gamma effect under the experimental conditions used." (PMID 21931722, 2011). "Furthermore, glioma stem cells recruited monocyte-derived macrophages by secreting CSCs-derived periostin, thereby supporting tumor growth 50; additionally, the loss of PTEN and NF1 in glioma stem cells upregulated LOX and chemokines, respectively, to attract TAMs 51,52." (PMID 39479456, 2024). "However, a recent report suggests that in Nf1-deficient neuroglial progenitor cells, CNS injury could be sufficient to induce glioma formation, indicating that independent injuries can promote tumor development in susceptible animals." (PMID 38804352, 2024). "That chromosome 7 monosomy and 7q22 deletions occur as common secondary events after hyperactivation of Ras oncogenes or mutation of the Ras-GAP protein neurofibromatosis-1 (NF-1) gene may explain the co-occurrence of cavernous malformations with both gliomas and tumors of Schwann cell origin." (PMID 34824953, 2021). "A recent study compared the molecular signatures of NF1-associated glioma (including OPG) with their sporadic counterpart, allowing to cluster low- and high-grade lesions and pinpointing distinct biological features that might have relevant implications for the development of novel treatments." (PMID 31739524, 2019). "Recent characterization of the mutational profiles of high-grade human gliomas by the Cancer Genome Atlas (TCGA) Research Network demonstrated that 23% of patient samples harboured somatic NF1 inactivating mutations or deletions, of which 64% represented NF1 heterozygous deletions." (PMID 23762429, 2013). "Mutations in genes including ROS1, ALK, NF1, KRAS, MEK, and CRAF have been identified across glioma subtypes, highlighting the necessity for molecular classification beyond traditional histopathology." (PMID 41514664, 2026). "Other pHGG subtypes include those that are ACVR1-mutant, histone wild-type, such as pleomorphic xanthoastrocytoma (PXA)-like gliomas enriched with BRAF mutations, and NF1-associated gliomas with receptor tyrosine kinase fusions." (PMID 40647519, 2025). "Gliomas arising in the setting of NF1 are driven by biallelic NF1 inactivation: tumors develop following somatic inactivation of the remaining wildtype allele through either the loss of heterozygosity (LOH) or a second tumor-acquired mutation." (PMID 40277798, 2025). "Inhibition of PI3K, which acts upstream of mTOR, was also shown to significantly reduce glioma proliferation and optic nerve volume in NF1 mouse models." (PMID 41294711, 2025). "High-grade glioma arising in NF1 occurs primarily in adults presenting a worse outcome compared to NF1-low-grade gliomas." (PMID 40277798, 2025). "In pediatric glioma research, GEMMs frequently incorporate mutations that disrupt key signaling pathways, including Ras, EGFR, Akt, Rb, PTEN, NF1, and PDGF signaling." (PMID 40647519, 2025).
glioma (continued). "Preclinical studies support MEK inhibition as a selective therapeutic strategy in NF1-mutant nervous system tumors including gliomas." (PMID 40985888, 2025). "AAV-K55 markedly enhanced tumor selectivity, reduced liver uptake, and demonstrated significant therapeutic efficacy in delivering the GRD-C24 transgene across multiple NF1 tumor models, including pNFs, MPNSTs, and gliomas." (PMID 41374990, 2025). "Patients with multiple gliomas in distinct locations had each tumor counted separately, with 112 total NF1-LGG included in this study." (PMID 40296988, 2025). "The consensus statement from the NF1 Optic Pathway Glioma Task Force in 2004 acknowledged that radiotherapy has the longest experience with the treatment of OPGs and addressed the pros and cons of radiotherapy." (PMID 40589683, 2025). "The Rb1 gene was the most commonly mutated gene, with P/LPSVs were noted in 6/12 (50%) RB patients; P/LPSVs were noted in the NF1 gene in 3 patients: 1/12 (8.3%) patients with RB and 2/3 (66.6%) patients with low-grade glioma." (PMID 40779059, 2025). "Aggressive subsets within wild-type gliomas were further defined by CDKN2A/B deletion (26.9%) and NF1 mutation (7.8%)." (PMID 41377022, 2025). "The NF1 gene, altered in approximately 20% of GBs, is a regulator of Ras activity in the RAS/MAPK signalling pathway associated with the development of tumours of the central nervous system and a short OS and prognosis." (PMID 41573648, 2025). "NF1 and PIK3CA gene mutations were reported to have a risk prognostic effect in breast cancer, while this analysis also showed association in glioma and lung cancers." (PMID 39277826, 2024). "To compare the subclonal diversity of primary cultures with differentiated glioma cells cultured in serum, we included the U87MG cell line derived from an IDH wildtype high-grade glioma with typical GBM mutations in the NF1, PTEN and TERT genes." (PMID 38414005, 2024). "In children, low-grade gliomas are predominant, while high-grade gliomas are more commonly seen in adults with NF1." (PMID 38893021, 2024). "Patients with NF1 are born with a germline inactivating mutation in one copy of the NF1 gene (monoallelic or heterozygous NF1 loss) but may acquire a ‘second-hit’ mutation (biallelic NF1 loss) during development in susceptible cell types to induce glioma formation." (PMID 38816530, 2024). "Work with MEK1/2 inhibitors such as selumetinib is encouraging and effective in the majority of NF1 participants with PNs or low-grade gliomas, and the drug was recently granted FDA approval for the treatment of NF1 PN." (PMID 39016685, 2024). "NF1 inactivation is associated with sensitivity to MEK inhibitor targeted therapy in low-grade and some high-grade gliomas." (PMID 39472976, 2024). "As the size and number of FASIs can fluctuate over time, early-stage gliomas can be mistaken for FASIs in patients with NF1." (PMID 39432071, 2024).